CRP (C-reactive protein)
Diseases named in the same sentence as CRP in open-access papers (continued):
Sharing a sentence is not in itself a finding about the gene and the disease.
Obesity (continued). "Obesity and the MetS risk in children have been recently associated with systemic inflammatory markers, in particular C-reactive protein (CRP), implying that low-grade inflammation can already exist in childhood and may be a potential link between the obesity and the MetS." (PMID 22315623, 2012). "Linear and logistic regression and dose-response curves were used to evaluate relations of tCys with obesity, insulin resistance and inflammatory markers including interleukin-6 (IL-6), tumor necrosis factor-alpha (TNF-α), monocyte chemoattractant protein-1 (MCP-1) and C-reactive protein (CRP)." (PMID 22984471, 2012). "Furthermore, with the inclusion of CRP, the power of sarcopenic obesity, sarcopenic nonobesity, or nonsarcopenic obesity to predict cognitive functioning was not significantly altered." (PMID 22611388, 2012). "However, some studies concluded that the relationship between CRP concentrations and insulin resistance was independent of obesity." (PMID 21167068, 2010). "Because patterns of obesity vary according to the level of socioeconomic development, it is feasible that the effects of income and education on CRP may also vary from country to country, independent of the effects of SES on obesity." (PMID 20137842, 2010). "Obesity but not the insulin resistance is determining factor for the serum CRP levels." (PMID 19222849, 2009). "However, evaluation of multivariate correlation showed that the beneficial effect of Paleolithic diet on C-reactive protein was independent of all other relevant study variables including measures of obesity such as body weight and subcutaneous fat thickness." (PMID 17081292, 2006). "This could indicate a potential protective effect of obesity in this specific context, although the lack of differences in sFLT-1 levels and CRP between the two groups suggests that other inflammatory and angiogenic pathways may remain unaffected in this model." (PMID 40362895, 2025). "Furthermore, BMI was found to have a relationship with semi-quantitative CRP readings among overweight individuals, which supports an earlier clinical suspicion of an occult inflammatory process—without waiting to diagnose obesity as an already alarming finding." (PMID 40565981, 2025). "Furthermore, obesity‐induced inflammation results in the production of pro‐inflammatory cytokines, such as interleukin‐6 (IL‐6), tumor necrosis factor‐alpha (TNF‐α), and C‐reactive protein (CRP), which contribute to an inflammatory TME conducive to cancer progression." (PMID 40922069, 2025). "Additionally, the sample consisted of non-obese individuals; thus, elevated SQ CRP levels could not be confounded with obesity." (PMID 40565981, 2025). "Obesity contributes to this pro-inflammatory milieu by promoting the release of cytokines such as interleukin-6 (IL-6), tumor necrosis factor-alpha (TNF-α), and C-reactive protein (CRP), which may adversely affect both the synovial environment and the fibrotic response within the joint capsule." (PMID 41007680, 2025). "In addition, CRP regulates the expression of key adipokines and inflammatory mediators, including adiponectin, TNF-α, leptin, IL-6, and PPAR-γ, which may underpin its involvement in insulin resistance, obesity, and metabolic syndrome." (PMID 40001459, 2025). "However, even a CRP level of 12 mg/dL may not be considered elevated for older age, obesity, and smoking (all of which are factors that may raise the CRP level)." (PMID 39496168, 2024). "However, findings have been inconsistent in canine obesity, where an increased CRP concentration has been observed in some, but not other studies of canine obesity, including one study where the CRP concentration was less in dogs with obesity." (PMID 39296580, 2024). "Interestingly, higher levels of CRP were found in women with PCOS regardless of obesity." (PMID 37893164, 2023).
Obesity (continued). "In addition, several studies have demonstrated a significant link between C-reactive protein (CRP), a useful marker of inflammation, and incident DM after adjusting for obesity indexes 7,8, whereas other studies have argued that such associations may be chiefly mediated by increased adiposity." (PMID 36860675, 2023). "Finally, parameters such as C-reactive protein, plasma glucose, and glycated hemoglobin (HbA1c) might be obesity-relevant; however, they were not included in this analysis as they are not routinely collected for PWH during follow-up visits in the Netherlands." (PMID 37392435, 2023). "A recent systematic review with meta-analysis, aimed at determining whether the inflammation in PCOS women was intrinsic to the disease or conversely related to the associated adiposity, concluded that circulatory CRP is elevated in PCOS women and that this was independent of obesity." (PMID 36079796, 2022). "However, the temporal nature of relationships could not be disentangled because obesity, CRP and walking limitations were measured at the same time." (PMID 35301057, 2022). "Thus, our finding of a potential pathway linking obesity and poor PF, via CRP, represents an important target for intervention which may reduce some of the negative consequences of obesity." (PMID 35301057, 2022). "Besides, CRP is not just a biomarker but also a crucial factor in obesity development." (PMID 34568498, 2021). "Obesity-related HFpEF obtained in our experimental conditions was associated with a subclinical pro-inflammatory status highlighted by significantly increased IL-6 and leptin plasma levels, a trend for increased TNF-alpha and decreased adiponectin/leptin ratio, but without CRP modifications." (PMID 33142857, 2020). "The associations of SRH with the development of metabolic abnormalities were stronger in individuals with obesity than those without especially in relation to any metabolic abnormality (p for interaction = 0.039), fatty liver (p for interaction < 0.001), and high CRP (p for interaction = 0.030)." (PMID 30609650, 2019). "However, we did evaluate the indicators of inflammation, such as IL 6 and CRP, for which we did not observe statistically significant changes between groups, indicating that an early age of obesity development and its longer duration did not worsen a systemic inflammation." (PMID 30022421, 2018). "Overweight and obesity was related to dyslipidemia already at baseline, i.e. elevated triglycerides (TG, p < 0.001), decreased high-density-lipoprotein-C (p = 0.009) and increased ultrasensitive-c-reactive-protein (usCRP, p < 0.001) independent of gestational diabetes prevalence." (PMID 27436227, 2016). "However, none of those studies implicate CRP in the relationship of obesity and cognitive function." (PMID 26863443, 2016). "It is also possible that since both CRP and IL-6 are nonspecific indicators of systemic inflammation, infections, injury, obesity or proinflammatory chronic conditions, or other sources of inflammation may have accentuated or masked the effects of traffic pollutant exposure." (PMID 25685160, 2015). "However, in agreement with our cumulative meta-analysis and previous standard meta-analyses, inclusion of patients using psychotropic medication and the lack of adjustment for overweight/obesity resulted in slightly larger effect size estimates between the levels of CRP, IL-6 and depression." (PMID 26065825, 2015). "RESULTS: Patients with obesity (experimental and control 1) exhibited higher macrophage accumulation (p<0.001), M1 polarization (p<0.001), insulin resistance, WBC, CRP, and M1 marker (PELI1) than patients without obesity." (PMID 41428159, 2025). "Circulating levels of inflammatory mediators, such as C-reactive protein (CRP) and its inducer interleukin (IL)-6, are increased in individuals with obesity compared to those without obesity." (PMID 40565915, 2025).
Obesity (continued). "Independent of obesity, PCOS is marked by low-grade inflammation: circulating levels of TNF-α, IL-6, IL-8 and C-Reactive Protein are elevated relative to controls." (PMID 40694958, 2025). "Elevated levels of inflammatory markers such as C-reactive protein (CRP), fibrinogen, TNF-α, and IL-6 have been observed in OSA patients, independent of obesity." (PMID 40428013, 2025). "Studies have shown that OSA patients demonstrate higher levels of inflammatory factors (CRP, fibrinogen, TNF-α, IL-6), regardless of obesity status." (PMID 40428013, 2025). "The lack of associations with elevated CRP might reflect the timing of sampling (which was later in pregnancy in the LMIC studies) or may be driven by the higher prevalence of infectious diseases in LMICs, and the lower prevalence of obesity, which can also elevate CRP." (PMID 38753813, 2024). "Researchers have found that sedentary time is positively correlated with C-reactive protein (CRP) levels, independent of physical activity and obesity." (PMID 38632571, 2024). "This included the “objective measures” reflecting inflammation (SJC,CRP), whereas ACPA-negative RA patients with obesity did not have more inflammation as assessed by SJC and CRP during the disease course compared to normal weight patients." (PMID 38321544, 2024). "For certain relationships, however, the highest percentages correspond to non-adjacency, suggesting weak connections between CRP and TGL (52%), HOMA-IR and HDLc (42%), and Obesity and HTN (38%)." (PMID 39717478, 2024). "If all lean subjects were evaluated together, in both sexes proxy measures of obesity, concentrations of insulin, non-HDL-C, CRP, homocysteine, cMSS5, and leukocyte counts showed a direct—and QUICKI, a significant—inverse association with AIP." (PMID 37508640, 2023). "For instance, women with PCOS display elevations in circulating C-reactive protein (CRP), which is 96% higher compared with controls, an effect which is independent of obesity." (PMID 37251667, 2023). "In patients without DM or obesity severe pneumonia, NLR, CRP, IL-6, insulin resistance indices, and hyperglycemia during hospitalization were associated with longer hospitalization." (PMID 37515156, 2023). "An adjunctive parameter was considered, i.e., CRP, which, though it is not an IDF criterion, is a well-known marker of inflammation (not only) in obesity." (PMID 37108620, 2023). "Subclinical inflammation, characterized by increased WBC counts, IL 6, and CRP levels, is a crucial feature of PCOS with or without obesity." (PMID 36677054, 2023). "However, no study has investigated how sex moderates the relationship between LLS (which may capture stressful life experiences in multiple domains) and physiological outcomes, such as BMI/obesity and CRP, particularly not in middle-aged and older African Americans." (PMID 35629167, 2022). "In our study, the Bacteroidetes enriched in PDC, which was positively correlated with serum C-reactive protein and systolic blood pressure and negatively correlated with HDL, plays a negative factor for obesity and its complications." (PMID 35719350, 2022). "A meta-analysis of the subjects’ inflammatory response data showed that training improved IL-6 levels and significantly reduced CRP levels in adolescents with obesity, but training did not improve TNF-α levels in adolescents with obesity." (PMID 36293806, 2022). "Although evaluation of CRP levels was not included in this study—because of the lack sufficient data—the observed association between obesity and high PUCAI score at diagnosis may suggest a so far unrecognized relationship between obesity, inflammation, and pediatric UC." (PMID 36498163, 2022). "Four of these are clinical variables derived from history (male sex, severe obesity, presence of constipation, and not being on PPI therapy) and two are laboratory values (Hb and CRP)." (PMID 33572940, 2021).
Obesity (continued). "Since obesity and/or metabolic syndrome have been reported to be associated with increased risk of HPV infection or its persistence, we have also evaluated whether or not the association between the hs-CRP level and LSIL regression differs based on the presence of overweight or insulin resistance." (PMID 33536377, 2021). "Inflammatory markers related to obesity and not PCOS status per se include: TNFα, soluble type 2 TNF receptor, IL-6, and high sensitive CRP." (PMID 33562271, 2021). "Subdividing people with obesity into MetsO and MHO, a negative correlation was also detected between MMP-2 levels, MMP-2/TIMP-2 ratio and CRP values in MetsO (r = − 0.26, p = 0.03, r = − 0.27, p = 0.03, respectively)." (PMID 34625635, 2021). "A meta-analysis showed that CRP level was higher in PCOS patients than in healthy women, independent of obesity." (PMID 33849562, 2021). "Obesity status was deemed important in a cohort of adolescent girls, because obese girls with PCOS without IR had higher levels of CRP compared to girls with normal BMI values with or without metabolic disorders." (PMID 35053629, 2021). "Sleep restriction, based on laboratory studies, is associated with a pre-inflammatory condition, which includes increase in inflammatory cytokines such as interleukins, Tumor Necrosis Factor (TNF) and C-reactive protein (CRP), regardless of obesity." (PMID 35004785, 2021). "Subjects with obesity, visceral adiposity, or sarcopenia were significantly older and had higher LDL-C, TG, CRP, and glucose levels, and HOMA-IR than those without." (PMID 34403431, 2021). "In a recent study, CRP was increased in young women with PCOS, irrespective of obesity, compared to their BMI-adjusted controls, suggesting a baseline risk of low-grade inflammation and CVD among PCOS-women." (PMID 35053629, 2021). "They reported that obesity, rather than OSA or nocturnal hypoxemia, is the key predictor of the elevated level of CRP in patients with OSA." (PMID 33809834, 2021). "It was concluded that the level of CRP does not correlate with the severity of OSA in male patients with OSA, but rather correlates independently with obesity." (PMID 33809834, 2021). "Inflammatory markers (C-reactive protein [CRP], lactate dehydrogenase [LDH], ferritin, and D-dimer) were compared between patients with and without obesity (body mass index [BMI] ≥30 kg/m2)." (PMID 33326480, 2020). "There are few studies that include CRP for identification of individuals with MHO and MUO since severe obesity is a potential inflammatory condition per se independent of metabolic alterations." (PMID 29385682, 2018). "Our analysis found that even after controlling for obesity, those with sleep disorders and reported sleep disturbances showed increased RDW and CRP levels compared to those without sleep disturbances." (PMID 30402295, 2018). "Serum concentrations of high sensitive C-reactive protein (hs-CRP) weresignificantly higher in obese than in non-obese PCOS patients at baseline, suggesting arelationship between elevated hs-CRP levels and obesity." (PMID 28042411, 2017). "CRP levels were also found to be surprisingly higher among COC users than non-users, which suggests a synergic effect between obesity and COCs use." (PMID 29033897, 2017). "In contrast, the present study showed that CRP predict CVD risk independent of the Framingham Risk Score variables, and in a pathophysiological perspective, our results indicate indirectly that interleukin-6-related pathways may play a role in overweight- and obesity related CVD." (PMID 26035431, 2015). "Baseline biomarkers in 2000-4 (CRP, IL-6, sTNFR2, leptin, lipocalin 2 and A-FABP) had significantly positive correlation with indices of obesity WC and BMI while adiponectin had significant negative correlation." (PMID 24205276, 2013).
Obesity (continued). "History of cardiovascular disease 1.42 (0.66,3.0.8), obesity 0.77 (0.48,1.25), LDL cholesterol mg/dL 1.0 (0.9, 1.01), smoking 1.11 (0.63, 1.97) and CRP levels (mg/dL) 0.96 (0.81, 1.14) were not independent predictor in this model." (PMID 21569369, 2011). "Importantly, biomarkers such as CRP, IL-6, TNF-α, and leptin are frequently elevated in individuals with overweight or obesity independent of dietary exposures." (PMID 41010537, 2025). "This study represents the first exploration of the effects of the HC and LC exercise protocols, with or without the consumption of BBR, on CRP, IL‐1β, NLRP3, and H19 in middle‐aged men with overweight or obesity and prediabetes, which can be considered an advantage." (PMID 39107107, 2024). "These two groups were clinically distinct—the inflammatory group had an increased swollen joint count (5.0), high CRP levels (1.0 mg/dL), and high DAS28-CRP (5.3), while the non-inflammatory group had a higher proportion of obesity (55%) and fibromyalgia (15%)." (PMID 39768516, 2024). "present the comparison of miR-193a, mir122, and mir155 expression levels among children with and without some metabolic status (including obesity, metabolic syndrome indices, and different levels of REE, different body composition, hyper-insulinemia, insulin resistance, and high hs-CRP respectively." (PMID 36859176, 2023). "In this way, cystatin C, hs-CRP, and NLR, which we can call inflammation markers, are higher in adolescents with both NW and OW PCOS than controls, supporting that PCOS develops in the inflammatory process, independent of obesity." (PMID 35657129, 2022). "In our sample, the higher rates of obesity among Hispanic vs. non-Hispanic girls were in line with findings from population-based studies and corresponded to higher total body fat mass, percent body fat, triglycerides, HOMA-IR, and CRP." (PMID 36172390, 2022). "However, regarding the increase in IL-6, CRP, and TNF-α in adolescents with obesity, resistance training (RT) did not lead to significant differences." (PMID 36293806, 2022). "Subgroup analyses were performed in different ages (<60 vs ≥60), gender (female vs male), history of smoking and drinking (Yes vs No), BMI (normal vs overweight or obesity), ESR (≥20 vs <20) and CRP (ESR ≥ 8 vs <8), and Kellgren–Lawrence grading (I/II vs III vs IV)." (PMID 30777926, 2019). "Subjects with NAFLD were more obese and had more of obesity-related metabolic aberrations than subjects without NAFLD, including impaired glucose homeostasis, hypertension, high triglyceride levels, low HDL and high CRP." (PMID 30133541, 2018). "Furthermore, commonly used measures of RA disease severity, CRP, and ESR are nonspecific, with increased concentrations observed in other chronic conditions and obesity." (PMID 27067270, 2016). "Obesity produces greater levels of systemic inflammatory factors, including adipose tissue macrophages, circulating lymphocytes, and pro-inflammatory cytokines (e.g., TNF-α, IL-6, TGF-β1, and C-reactive protein), than is produced in non-obese states." (PMID 27487262, 2016). "CRP does not cross the blood-brain barrier (BBB) in trace amounts; however, during systemic inflammation and obesity, CRP may increase paracellular permeability of the BBB and impair BBB function." (PMID 23826157, 2013). "Compared with non-obese patients with PCOS, those with obesity demonstrated more severe inflammatory responses, including increased levels of IL-6, TNF-α, neutrophil-to-lymphocyte ratio (NLR), high-sensitivity C-reactive protein (hs-CRP), and mean platelet volume (MPV) levels." (PMID 41239503, 2025). "Another recent publication reported that patients with metabolic diseases (obesity, type 2 diabetes, metabolic syndrome, cardiovascular disease, and nonalcoholic fatty liver disease) had a significant decrease in TNF-α plasma levels with CoQ10 supplementation but not CRP or IL-6." (PMID 31083534, 2019).